EZH2 (enhancer of zeste 2 polycomb repressive complex 2 subunit)
Diseases named in the same sentence as EZH2 in open-access papers (continued):
Sharing a sentence is not in itself a finding about the gene and the disease.
glioma (continued). "In vitro, only extended treatment (to one week) of DMG H3K27M cells with EZH2 inhibitors had significant effects on the proliferative and survival capabilities of glioma cells (independent of mutational status)." (PMID 36403059, 2022). "EZH2 has been reported as a potential therapeutic target for H3K27M-mutant pediatric gliomas." (PMID 36230759, 2022). "• EZH2 has also been identifiedas a promising targetfor H3K27M mutant pediatric gliomas." (PMID 35786935, 2022). "The statistical analysis illustrated that the EZH2/p65 axis was dramatically relative to age, glioma grades and EGFR expression, suggesting that high levels of both p65 and EZH2 expression are correlated to a higher risk of glioblastoma development and progression." (PMID 36263173, 2022). "The results showed only EZH2 significantly elevated in grade IV gliomas." (PMID 36309750, 2022). "USP1-mediated stabilization of EZH2 promotes the occurrence and development of glioma." (PMID 36230759, 2022). "We, therefore, hypothesized that EZH2 inhibition by GSK126 renders DMG glioma cells dependent on cholesterol biosynthesis, thus giving the possibility to explore statins or other lipid reducing drugs as treatment option in this pathology." (PMID 35300150, 2022). "EZH2 analysis might, therefore, be of clinical value for risk stratification, especially in patients with IDH1 R132H-negative gliomas." (PMID 36292072, 2022). "High EZH2 immunoexpression was demonstrated in 27 (48.2%) gliomas." (PMID 36292072, 2022). "High EZH2 protein expression was observed in 27 (48.2%) out of 56 gliomas." (PMID 36292072, 2022). "The prognostic value of EZH2 as a tissue protein marker for gliomas was also explored." (PMID 36292072, 2022). "Previous reports revealed that EZH2 acts as an oncogene in GB, promoting multiple glioma cellular processes, including cell cycle, cell invasion, and angiogenesis, which is thought to be responsible for cancer cells survival, drug resistance and tumor recurrence." (PMID 36430394, 2022). "In glioma tissues, MiR-133b was downregulated, but EZH2 was increased." (PMID 36536420, 2022). "In gliomas, EZH2 is involved in proliferation, invasion, and migration." (PMID 35197928, 2022). "EZH2 is suggested to have a pro-tumorigenic role in gliomas (both pediatric and adult)." (PMID 35395831, 2022). "NEAT1 lncRNA is induced by the EGFR pathway in glioma which then sequesters the chromosome modification enzyme EZH2 to facilitate repression of certain target genes and to promote nuclear translocation of β-catenin, thus activating the WNT/β-catenin oncogenic pathway in GBM." (PMID 36009578, 2022). "Although some studies have investigated the role of EZH2 on macrophages polarization, the conclusion varies in different settings, i.e., suppression of EZH2 remodeled macrophages toward pro-inflammatory M1 inhibiting tumor proliferation in glioma." (PMID 35432300, 2022). "Though a few recent investigations suggest that EZH2 could play a pro-tumorigenic role in gliomas, specifically in DMG, the exact contribution of EZH2 in this disease is lacking partly due to the absence of appropriate in vivo mouse models." (PMID 35395831, 2022). "In conclusion, EZH2 is highly expressed in higher grade gliomas." (PMID 36292072, 2022). "In addition, EZH2 is inhibited in gliomas, mediated in a PRC2-dependent manner through miRNA-454-3p, immunosuppression or M2-like macrophage polarization." (PMID 36135315, 2022). "It was also found that MSCs-derived exosomes transmitting miR-133b into glioma cells could inhibit EZH2 expression by disrupting the Wnt/β-catenin signaling pathway, thereupon repressing proliferation, invasion and migration of glioma cells." (PMID 35095909, 2021). "Although the EZH2 expression level was correlated with other clinical parameters, our results demonstrate that EZH2 expression also may provide an independent predictor of overall survival in glioma patients." (PMID 33277782, 2021).
glioma (continued). "EZH2 was variably secreted in the nuclei of tumor cells in Grades II to IV gliomas." (PMID 34745848, 2021). "Most of the articles were indexed in PubMed and PMC with strict inclusion criteria being the immunomodulatory and anti-inflammatory effect of EZH2 in the glioma microenvironment which may be of biomarker and therapeutic importance." (PMID 34745848, 2021). "They indicated that MSC-derived exosomal miR-133b was capable of blocking glioma cell proliferation, invasion, and migration as well as tumor growth via the suppression of EZH2 through the blockade of the Wnt/β-catenin signaling pathway in in vitro as well as in vivo experiments." (PMID 34745848, 2021). "Studies on EZH2-Ras-NF-κB signaling pathways in glioma are warranted." (PMID 34745848, 2021). "Hence, we established a direct interaction between curcumol treatment and FOXD2-As1-induced EZH2 activity in glioma cells." (PMID 34739394, 2021). "Univariate Cox analysis revealed that EZH2 expression, PRS type, Histology, Grade, Age, Chemo status, IDH mutation and 1p19q status were all associated significantly with the overall survival of glioma patients." (PMID 33277782, 2021). "Specifically, the blockade of EZH2 activity inhibited aerobic glycolysis in glioma cells." (PMID 34745848, 2021). "Furthermore, the ESTIMATE and Timer Database scores indicated correlation of EZH2 expression with a more immunosuppressive microenvironment for glioblastoma than for low grade glioma." (PMID 33277782, 2021). "The same authors described that EZH2 inhibition blocked cell cycle progression in glioma cells, consistent with the effects elicited by HOTAIR siRNA, suggesting that HOTAIR might regulate cell cycle progression through EZH2." (PMID 34576322, 2021). "EZH2 is well recognized as an essential modulator of cell invasion as well as metastasis in glioma." (PMID 34745848, 2021). "In glioma, studies have shown that EZH2 could be regulated by many miRNAs, such as miR-9, miR-133b and miR-1265." (PMID 33901010, 2021). "Bioinformatics analysis revealed that miR-133b was capable of influencing the EZH2 gene in glioma." (PMID 34745848, 2021). "Furthermore, EZH2 is involved in glioma initiation and progression as well as in the formation, maintenance, and plasticity of GSCs." (PMID 34745848, 2021). "We further investigated whether curcumol inhibited the malignant behavior of glioma cells by reducing FOXD2-As1-induced EZH2 activity." (PMID 34739394, 2021). "miR-520b/EZH2 mediates circular RNA TTBK2-accelerated glioma." (PMID 33758783, 2021). "Overall, our study demonstrates that expression of EZH2 is a potential prognostic molecular marker of poor survival in glioma and identifies signalling pathways and immune checkpoints regulated by EHZ2, suggesting a direction for future application of immune therapy in glioma." (PMID 33277782, 2021). "EZH2 is a promising therapeutic as well as prognostic biomarker for the treatment of glioma." (PMID 34745848, 2021). "Furthermore, data from GTEx database verify that EZH2 expression is elevated in tumour from patients with glioma." (PMID 33277782, 2021). "To test whether the inhibition of PD-L1 mediated by HOTAIR affects the immune sensitivity of tumor cells, we co-cultured glioma cells treated with EZH2 siRNA or HOTAIR siRNA with activated human peripheral blood mononuclear cells (PBMCs)." (PMID 34887871, 2021). "They indicated that EZH2 triggers glioma invasiveness via transcriptional regulation of AXL." (PMID 34745848, 2021). "Overall, our results indicate that EZH2 may serve as a favourable prognostic factor for glioma patients." (PMID 33277782, 2021). "Moreover, secretion of BMI1 as well as EZH2 was observed as an independent prognostic factor for overall survival in glioma patients." (PMID 34745848, 2021).
glioma (continued). "PHF19 could form the PRC2 with Ezh2, EED, and SUZ12, knockdown of the PHF19 gene suppressed Ezh2 phosphorylation and proliferation in glioma cells." (PMID 35003347, 2021). "EZH2 contributes to TMZ resistance in gliomas and is essential for GSC phenotypes." (PMID 34586728, 2021). "EZH2 has an important impact on stem-like cell maintenance of glioma." (PMID 34739394, 2021). "Furthermore, low EZH2 expression in glioma patients from the CGGA database was significantly related to better pathologic stage, histological grade and satisfactory survival time, which supports findings from other studies." (PMID 33277782, 2021). "Furthermore, GSK343 treatment in normal glioma cells not only reduced the protein quantities of EZH2 but also downregulated the secretion of c-MYC." (PMID 34745848, 2021). "The EZH2-miR-328/β-catenin signaling cascade could act as an innovative therapeutic biomarker for glioma." (PMID 34745848, 2021). "DLGAP1-AS1 promoted glioma progression through miR-1297 sponging and EZH2 regulation." (PMID 33901010, 2021). "DLGAP1-AS1 could enhance glioma cell proliferation, migration and invasion by sponging miR-1297 to regulate EZH2." (PMID 33901010, 2021). "In this study, we investigated the prognostic value of EZH2 in glioma." (PMID 33277782, 2021). "We believe that FOXD2-As1 might be a molecular target of curcumol, and that curcumol performs its functions in glioma cells by repressing FOXD2-As1-induced EZH2 activity." (PMID 34739394, 2021). "Furthermore, the silencing of EZH2 secretion by using RNA interference in U87 human glioma cells triggered apoptosis and cell cycle arrest in the G0/G1phase." (PMID 34745848, 2021). "Next, glioma cells were co-cultured with macrophages in vitro to study whether the expression of EZH2 in glioma could polarize macrophages into M2." (PMID 33363140, 2020). "Next, we continued to validate whether EZH2 could promote glioma development by promoting M2 macrophage polarization in vivo through tumorigenesis model in nude mice." (PMID 33363140, 2020). "EZH2 was silenced by lentivirus treatment in glioma cell line A172." (PMID 33363140, 2020). "Furthermore, down-regulation of EZH2 suppresses glioma growth through a negative regulatory effect on the β-catenin signaling pathway." (PMID 32746854, 2020). "Collectively, downregulation of EZH2 in glioma cells suppressed the polarization of M2 macrophages." (PMID 33363140, 2020). "miR-454-3p, a down-regulated miR in glioma, was found to be increased after silencing of EZH2." (PMID 33363140, 2020). "In this study, we were intended to find out whether action modes of EZH2 affected glioma cells and their effects on macrophage polarization." (PMID 33363140, 2020). "Considering these findings, a hypothesis was drew that EZH2 might participate in macrophage polarization in glioma via miR-454-3p/YTHDF2/PTEN axis." (PMID 33363140, 2020). "Therefore, EZH2/miR-454-3p/PTEN axis was involved in glioma progression, especially macrophage polarization." (PMID 33363140, 2020). "Abnormal up-regulation of the EZH2 gene in glioma cells induces invasion and metastasis in GBM." (PMID 32746854, 2020). "We speculate that EZH2 and miR-454-3p may be promising new directions in the development of therapeutic treatments for glioma." (PMID 33363140, 2020). "LncRNA HOXB13-AS1 promotes glioma progression by regulating HOXB13 gene methylation through EZH2." (PMID 33109776, 2020). "However, considering many potential miRs governed by EZH2, one challenge in understanding functional EZH2 contributions in glioma cell behaviors depends on the identification of bona fide molecular targeted miRs." (PMID 33363140, 2020). "In glioma cells, inhibition of the EZH2 activity suppresses aerobic glycolysis." (PMID 32448308, 2020). "In addition, downregulation of EZH2 has inhibitory impacts on glioma growth via suppression of the β-catenin signaling pathway." (PMID 31842978, 2019).
glioma (continued). "In addition, the EZH2 gene presents with abnormally high expression in glioma, which is a key regulator of invasion and metastasis." (PMID 31842978, 2019). "Altogether, these results strongly support an EZH2‐mediated EMX2‐HOX switch in glioma." (PMID 31468686, 2019). "Taken together, our findings revealed that MSC-derived exosomes over-expressing miR-133b could inhibit the progression of glioma by targeting EZH2 through the Wnt/β-catenin signaling pathway." (PMID 31842978, 2019). "EZH2 and EMX2 levels showed a significant anti‐correlation in multiple glioma patient datasets, supporting the hypothesis that EZH2 represses EMX2 in patients (and EV4A and C)." (PMID 31468686, 2019). "In addition, both low and high‐grade glioma showed inverse correlation between EZH2 and EMX2 mRNA levels (Fig EV4C)." (PMID 31468686, 2019). "However, aberrant expression of HOX genes, which are no longer regulated by EZH2 upon transformation, cannot explain the pathological function gained by EZH2 in glioma." (PMID 31468686, 2019). "Restoration of miR-708 could counteract EZH2 overexpression effect on glioma cell growth and invasion." (PMID 31171769, 2019). "Overall, elevated EZH2 expression was identified in glioma tissues and cells." (PMID 31842978, 2019). "We examined MELK, EZH2, and NF-κB expression by immunohistochemistry and demonstrated that MELK, EZH2, and NF-κB were abundantly enriched in the nuclei of high-grade gliomas with the average score ranking from 1.2 to 1.8, compared with the low-grade and normal adjacent tissues." (PMID 31380279, 2019). "Moreover, a recent study also demonstrated that EZH2 is related to the development of glioma and affects glioma cell invasion and metastasis." (PMID 31842978, 2019). "After altering the expression of EZH2 in U87 cells, we employed RT-qPCR and Western blot analysis, which showed increased EZH2 expression in glioma cells treated with oe-EZH2, whereas decreased EZH2 expression was noted in U87 cells treated with sh-EZH2 (p < 0.05)." (PMID 31842978, 2019). "Collectively, the obtained results suggested that MSC-derived exosomes carrying miR-133b could attenuate glioma development via disrupting the Wnt/β-catenin signaling pathway by inhibiting EZH2, which provides a potential treatment biomarker for glioma." (PMID 31842978, 2019). "Additionally, MSC-derived exosomes containing miR-133b repressed glioma cell proliferation, invasion, and migration by inhibiting EZH2 and the Wnt/β-catenin signaling pathway." (PMID 31842978, 2019). "Additionally, the data in our study further indicated that miR-133b targeted the EZH2 gene, as evidenced by upregulated levels in glioma tissues and cells." (PMID 31842978, 2019). "miR-133b was downregulated while EZH2 was upregulated in glioma tissues and cells." (PMID 31842978, 2019). "In addition to assessing the role of MELK/EZH2/NF-κB axis in different histopathological gliomas, additional studies will investigate their function in genetic subgroups of glioma." (PMID 31380279, 2019). "Interestingly, MELK activity together with FOXM1 has been shown to positively regulate both SOX2 and EZH2 in other tumours, such as glioma and medulloblastoma." (PMID 29437778, 2018). "Taken together, these data indicate that miRNA-driven EZH2 repression may provide evidence of the molecular mechanism for gliomagenesis and the novel therapeutic targets for glioma." (PMID 29221202, 2017). "Study also demonstrated an interaction between DNMT1 and EZH2 in gastric cancer and glioma cells." (PMID 28360411, 2017). "This evidence, along with the findings of our meta-analysis, may help to reveal the multiple roles of EZH2 in glioma development and to establish EZH2 as a useful biomarker for prognosis." (PMID 27880940, 2017). "We aimed to comprehensively evaluate the prognostic role of EZH2 in glioma by meta-analysis." (PMID 27880940, 2017). "Recent studies demonstrated that EZH2 could contribute to glioma progression by more extensive mechanisms." (PMID 27880940, 2017).
glioma (continued). "Furthermore, GSK343 treatment in normal glioma cells not only decreased the protein level of EZH2, but also depressed the expression of c-myc." (PMID 29228694, 2017). "Importantly, the effection of miR-524-5p and miR-324-5p on cell proliferation and TMZ chemosensitivity in glioma were reversed by expression of EZH2 cDNA." (PMID 29221202, 2017). "Moreover, the depletion of EZH2 expression by RNA interference produced anti-glioma effects both in vitro and in vivo." (PMID 29228694, 2017). "The biological role and prognostic significance of EZH2 were extensively investigated in gliomas." (PMID 27880940, 2017). "Over all, these findings suggest that EZH2 specific miRNAs miR-524-5p and miR-324-5p may play an important role in glioma development." (PMID 29221202, 2017). "Thus, the detailed mechanism involved in EZH2 specific miRNAs in glioma progression needs further investigation." (PMID 29221202, 2017). "Taken together, these results suggested that both PVT1 and EZH2 expression levels were positively correlated with glioma malignancy, and may play an important role in glioma progression." (PMID 29046366, 2017). "Thus, we suspected that miR-328 epigenetic silencing by EZH2 in gliomas was more complex involving both histone modifications and DNA methylation." (PMID 27385092, 2016). "Moreover, si-miR-328 largely abrogated si-EZH2 effects on glucose metabolism in U87 and U251 glioma cells." (PMID 27385092, 2016). "Here, we found that EZH2 was essential for glioma cell aerobic glycolysis." (PMID 27385092, 2016). "Finally, miR-328 largely abrogated EZH2 effects on β-catenin expression and glucose metabolism in glioma cells." (PMID 27385092, 2016). "Since our previous report indicated that EZH2 inhibition suppressed glioma cell growth by regulating cell cycle progression, we hypothesized that there was a similar phenomenon in HNSCC." (PMID 26378043, 2015). "However, in a cohort which includes low grade gliomas, significant survival benefits were observed for patients with low EZH2, PHF19, CBX8 and PHC2 expression, and high CBX7, CBX6, RYBP and EZH1 expression." (PMID 24260522, 2013). "Here we show that EZH2 is expressed in human glioma and correlates with malignancy." (PMID 23077658, 2012). "To evaluate our hypothesis that EZH2 also acts through methylation-independent mechanisms we performed a gene microarray assay of U87MG glioma cells treated with DZNep." (PMID 23077658, 2012). "We first analyzed EZH2 expression in glioma by immunohistochemistry." (PMID 23077658, 2012). "Many of the TAPP were not differentially expressed in the hypoxic cells but nine TAPPs from the glioma cells (Aim2, Art-4, EphA2, EZH2, Fosl1, PTH-rP, Sox11, Whsc2 and YKL-40) consistently exhibited increased mRNA presence after culturing the cells in response to hypoxia." (PMID 22957023, 2012). "The weak EZH2 expression in low grade gliomas could possibly be due high presence of miR-101 which is known to repress EZH2." (PMID 23077658, 2012). "Consequently, inhibition of EZH2 by short hairpin RNA (shRNA)-mediated knockdown or 3-Deazaneoplanocin A (DZNep) suppresses growth in glioma animal models." (PMID 23077658, 2012). "Silencing of EZH2 reduced glioma cell proliferation and invasiveness." (PMID 23077658, 2012). "We thus conducted gene microarray analyses of U87MG glioma cells after EZH2 knockdown." (PMID 23077658, 2012). "This indicates a potential dual role for EZH2 in endothelial cells and in glioma cells." (PMID 21297974, 2011). "Increased EZH2 expression correlated with glioma grade and glioma recurrence, suggesting that EZH2 could be a marker for glioma aggressiveness." (PMID 21321380, 2010). "In addition, these 3 independent studies all showed a highly significant correlation between EZH2 overexpression and gliomas." (PMID 20920292, 2010).